CETP (cholesteryl ester transfer protein)
Diseases named in the same sentence as CETP in open-access papers (continued):
Sharing a sentence is not in itself a finding about the gene and the disease.
breast carcinoma (10 papers, 2010 to 2025). "The possible risk-promoting effects of raised LDL-cholesterol and CETP-mediated raised HDL-cholesterol have implications for breast cancer prevention and clinical trials." (PMID 30262900, 2018). "Instrumental variable analysis with HDL-cholesterol-raising variants in CETP suggested a small risk-increasing effect on breast cancer and ER-positive disease; however, possible bias from pleiotropy cannot be excluded." (PMID 30262900, 2018). "HDL-cholesterol-raising variants in the gene encoding the target of CETP inhibitors are associated with higher risk of breast cancer (OR 1.07 [1.03–1.11] P = 0.001) and ER-positive breast cancer (OR 1.08 [1.03–1.13] P = 0.001)." (PMID 30262900, 2018). "However, it should be noted that recent Mendelian randomization studies have revealed opposite findings, by demonstrating the association of CETP downregulation with an increased risk of breast cancer." (PMID 33805921, 2021). "We find possible risk-increasing effects of raised LDL-cholesterol and CETP-mediated raised HDL-cholesterol that may have implications for breast cancer prevention." (PMID 30262900, 2018). "Suppression of CETP led to a notable inhibition in the growth of triple-negative breast cancer, a breast cancer subtype devoid of hormone receptors, which are typically targeted by endocrine therapies, resulting in an 86% reduction in tumor size." (PMID 39193372, 2024). "About eight years ago, CETP was identified as a potential molecular target for inducing cell death in estrogen-positive breast cancer cells." (PMID 39057711, 2024). "It was demonstrated that CETP contributes to better survival of breast cancer cells and promotes their resistance to apoptosis." (PMID 33805921, 2021). "Subsequent hierarchical clustering suggested that a number of those genes (including PPARG, FGF2, APOB, CRHBP, CETP, and RXRG) were significantly associated with breast cancer that appeared repeatedly in different GO-terms." (PMID 21059268, 2010). "A risky role for CETP was found in other studies of breast cancer, GC, and colorectal cancer." (PMID 39193372, 2024). "Here, the authors utilise data from more than 400,000 participants in two-sample Mendelian randomization to assess the link between blood lipids and breast cancer risk, and they find risk-promoting effects of raised LDL-cholesterol and CETP-mediated raised HDL-cholesterol." (PMID 30262900, 2018). "Thus, further studies are needed to address if CETP protein could serve as a serum marker for those breast cancer‐related surgery patients, who are likely to develop LE and related adipose tissue accumulation." (PMID 39394863, 2024). "In contrast, Apo A1, CETP, and CD36 protein concentrations were broadly similar between breast cancer and control women." (PMID 34503091, 2021). "None of the four clinical trials of CETP inhibitors published by May 2018 have reported associations with breast cancer occurrence, although the proportion of women (19.2% across trials) and the short follow-up of up to 4.1 years pose limitations on the detection of potential cancer-related effects." (PMID 30262900, 2018). "Despite these constraints, we found a number of biologically meaningful, differentially expressed genes related to HIST1, HIST2 proteins, and some other such as PPARG, FGF2, APOB, CRHBP, CETP, and RXRG in breast cancer tissue compared to corresponding adjacent normal breast tissue." (PMID 21059268, 2010).
endothelial dysfunction (10 papers, 2012 to 2025). In vascular diseases, endothelial dysfunction is a systemic pathological state of the endothelium (the inner lining of blood vessels) and can be broadly defined as an imbalance between vasodilating and vasoconstricting substances produced by (or acting on) the endothelium. "In human studies, a reverse correlation has been found between CETP gene polymorphisms and/or CETP activity and blood pressure, endothelial dysfunction, large and small vessel strokes, and intracerebral hemorrhage." (PMID 39201274, 2024). "Aim of the present study was to assess the ability of HDL obtained from CETP-deficient subjects to protect endothelial cells from the development of endothelial dysfunction." (PMID 24830642, 2014). "The present study was undertaken to evaluate the ability of HDL obtained from CETP-deficient subjects to protect endothelial cells from the development of endothelial dysfunction." (PMID 24830642, 2014). "CETP induced ER stress is also associated with endothelial dysfunction." (PMID 33430172, 2021). "In addition, CETP has been associated with mitochondrial oxidant production, respiratory capacity, inflammatory processes, phagocytosis, vascular oxidative stress, and endothelial dysfunction." (PMID 39201274, 2024). "The presence of CETP in endothelial cells can generate vascular oxidative stress and induce endothelial dysfunction." (PMID 35265678, 2022). "The reduced maximum relaxation in response to acetylcholine in aortas from CETP-transgenic mice, support that this mouse represents a model of endothelial dysfunction." (PMID 33430172, 2021). "Little is known on the effect of pharmacological or genetic CETP inhibition on HDL capacity to prevent endothelial dysfunction." (PMID 24830642, 2014). "In turn, in the E3L.CETP mice, impaired Ach-induced vasodilation was already detected in the AA in 14-week-old male and 22-week-old female mice, indicating accelerated, age-dependent endothelial dysfunction development in E3L.CETP mice vs control C57BL/6J mice." (PMID 40240752, 2025). "Based on detected DEPs, it was suggested that accelerated age-dependent endothelial dysfunction development in E3L.CETP mice (also more accelerated in male vs female E3L.CETP mice) could be related to increased inflammation and weakening of antioxidant defence in plasma." (PMID 40240752, 2025). "In contrast, in the young E3L.CETP mice, the Ach-induced response of the aorta was weakly affected by L-NAME in vivo, until the age of 14 weeks and 22 weeks (the age when endothelial dysfunction appeared) in the male and female mice, respectively." (PMID 40240752, 2025).
Hepatic steatosis (10 papers, 2013 to 2024). Steatosis is a term used to denote lipid accumulation within hepatocytes. "However, the underlying mechanisms by which inhibition of CETP prevents hepatic steatosis and steatohepatitis deserve further investigation." (PMID 25486007, 2014). "In the current study, the M1 cluster expressed metabolism-associated genes, such as CETP, LIPA, and APOE, suggesting that a potential interactant between M1 cluster and hepatic steatosis in ALC and HBV-related cirrhosis." (PMID 36817578, 2023). "Nevertheless, our data seem counterintuitive, as previous studies did report a decrease in CETP upon other interventions that reduce hepatic steatosis." (PMID 31292457, 2019). "In this study, we showed that inhibition of CETP by the Fc-CETP6 vaccine markedly reduced the occurrence of HFC diet-induced hepatic steatosis and steatohepatitis in rabbits." (PMID 25486007, 2014). "Hepatic steatosis is accompanied by hepatic inflammation, reflected by plasma cholesteryl ester transfer protein (CETP) levels." (PMID 24086738, 2013). "The potential t response heterogeneity to human ApoB and CETP transgenes in LGMD2B might be of interest ase ApoB dyslipoproteinemia is also prevalent in hepatic steatosis, fibrosis, and fat infiltration." (PMID 39138561, 2024). "Patients with hepatic steatosis also showed higher CETP activity, indicating that CETP inhibition may be regarded as a target to improve NASH." (PMID 25486007, 2014). "Importantly, we observed that inhibition of DHCR24 by SH42 prevented high‐fat diet‐induced hepatic steatosis in E3L.CETP mice but not in LXRα‐deficient mice." (PMID 37357756, 2023). "In addition, patients with hepatic steatosis also showed higher CETP activity." (PMID 25486007, 2014). "Liver macrophages largely contribute to hepatic CETP expression, and attenuation of hepatic steatosis, accompanied by attenuation of liver inflammation, as reflected by reduced macrophage content, by the anti-dyslipidemic drug niacin decreased hepatic CETP expression and the plasma CETP level." (PMID 24086738, 2013). "In conclusion, combined GIPR/GLP1R agonism additively attenuates hepatic steatosis and lowers hepatic inflammation, ameliorating liver injury during the development of NAFLD in E3L.CETP mice." (PMID 37379656, 2023). "We interpretate that GIPR and GLP1R agonism additively attenuate hepatic steatosis, lower hepatic inflammation, ameliorate liver injury, together preventing NAFLD development in humanized APOE∗3-Leiden.CETP mice." (PMID 37379656, 2023). "The current study in humanized E3L.CETP mice demonstrates that GIPR and GLP1R agonism additively attenuate hepatic steatosis, lower inflammation and ameliorate liver injury in the context of HFHC diet-induced NAFLD development." (PMID 37379656, 2023).
Abdominal obesity (7 papers, 2011 to 2023). Excessive fat around the stomach and abdomen. "We conclude that a diet low in SFA might help reduce the genetic risk of central obesity confirmed by CETP and LPL genetic variants." (PMID 35807893, 2022). "The minor Val allele of Ile405Val in the CETP gene was associated with both a decreased prevalence of low HDL-cholesterol levels (PR/allele 0.76, 95%CI 0.69; 0.86) and a decreased prevalence of abdominal obesity (PR/allele 0.90, 95%CI 0.83; 0.97)." (PMID 21767357, 2011). "The presence of the minor allele has been associated with increased risk of developing central obesity, increased fat mass, waist circumference, and waist-to-hip ratio, as well as reduced HDL concentrations, enhanced CETP activity, and increased intimal wall thickness of the carotid arteries." (PMID 36986146, 2023). "VLDL increased more in the men and women with abdominal obesity so CETP activity in these subjects might be lower." (PMID 24314230, 2013). "Two SNPs, CETP Ile405Val and APOE Cys112Arg, were associated with both the prevalence of low HDL-cholesterol level (Ile405Val P = < .0001; Cys112Arg P = 0.001) and with the prevalence of abdominal obesity (Ile405Val P = 0.007; Cys112Arg P = 0.007)." (PMID 21767357, 2011).
Cirrhosis (7 papers, 2012 to 2025). A chronic disorder of the liver in which liver tissue becomes scarred and is partially replaced by regenerative nodules and fibrotic tissue resulting in loss of liver function. "Previous studies support the hypothesis that LCAT, CETP, HL, apoA-I and apoA-IV are reduced in patients with liver disease and cirrhosis." (PMID 32927635, 2020). "Patients with cirrhotic end-stage liver disease have lower levels of circulating LCAT, besides alterations in CETP and HL activities, which raises the possibility that defective lipoprotein remodeling and catabolism may contribute to the generation of LP-Z in cirrhosis." (PMID 35268313, 2022). "While it is tempting to speculate on an association between LTIP and HCV due to these relationships between HCV-MTP-CETP and LTIP-CETP, the decreased LTIP expression is more likely to be associated with hepatic scarring due to the previously reported increase in CETP in cirrhosis." (PMID 22761838, 2012).
heart failure (7 papers, 2018 to 2024). Inability of the heart to pump blood at an adequate rate to meet tissue metabolic requirements. "Instead, we found that lower CETP levels decreased the risk of CHD, angina, intracerebral haemorrhage, and heart failure in both ancestry groups." (PMID 38906890, 2024). "A Cohort‐observational study involving 25 patients with heart failure showed that CETP level was low in patients with severe heart failure, suggesting CETP's protective effect against aggravation and severity of heart failure." (PMID 37249296, 2023). "Therefore, APOE∗3-Leiden.CETP mice cannot be used for studying cardiovascular events such as heart failure." (PMID 37356205, 2023).
hyperalphalipoproteinemia (7 papers, 2011 to 2021). An autosomal dominant genetic condition caused by mutation(s) in the CETP gene, encoding cholesteryl ester transfer protein. "We previously reported that patients with hyperalphalipoproteinemia (HALP) caused by CETP deficiency (CETP-D), who also showed similar lipid profiles to CETP inhibitor-treated patients, were not protected against CVD." (PMID 29304079, 2018). "Tietjen and colleagues showed that rare coding and splicing mutations on CETP were enriched in persons with hyperalphalipoproteinemia and segregated with elevated HDL-C in families." (PMID 23656756, 2013). "The importance of plasma CETP in lipoprotein metabolism was demonstrated by the discovery of CETP-deficient subjects with severe hyperalphalipoproteinemia." (PMID 21609439, 2011). "Defects in CETP are reported to be the cause of hyperalphalipoproteinemia 1 (HALP1), a disease characterized by abnormally elevated levels of HDL-C." (PMID 30263045, 2018). "Genetic CETP deficiency is caused by mutations in the CETP gene (OMIM 607322) that is located on chromosome 16q21, and is the most important and common cause of hyperalphalipoproteinemia in the Japanese." (PMID 21609439, 2011).
Hyperglycemia (7 papers, 2015 to 2024). An increased concentration of glucose in the blood. "However, hyperglycaemia per se could also activate CETP, since glycation of lipoproteins increases CETP activity." (PMID 25725623, 2015).
asthma (6 papers, 2015 to 2024). "For asthma, there was strong support for a directional discordance, with lower CETP significantly decreasing the risk in Europeans, but increasing the risk in East Asians." (PMID 38906890, 2024). "We found a protective effect of lower CETP on asthma in Europeans (OR 0.95, 95%CI 0.91; 0.99), and a harmful effect in East Asians (OR 1.26 95%CI 1.16; 1.36)." (PMID 38906890, 2024). "After accounting for multiple testing, we observed a differential effect of lower CETP levels on asthma, and lung cancer (interaction p-value < 1.6 × 10−3)." (PMID 38906890, 2024). "The serum levels of SAA1, FGA, and SAP in the EGPA group were significantly elevated as compared to the healthy control and severe-asthma groups, while the serum CETP was significantly lower in the EGPA group compared with the severe-asthma group." (PMID 35757752, 2022). "The combination of SAA1, FGA, SAP, and CETP as biomarkers for differential diagnosis of asthma had an AUC of 0.921, a sensitivity of 78.13%, and a specificity of 100%, which were all larger than single markers." (PMID 35757752, 2022). "In our study, we found that serum CETP levels in patients with the EGPA group were significantly lower than those in the severe-asthma group." (PMID 35757752, 2022). "Lower plasma concentration of CETP has been previously linked to an increased incidence of asthma in non-randomised observational studies." (PMID 38906890, 2024). "Furthermore, it is important to consider to what extent the difference between the effects of CETP on asthma and lung cancer reflect genetic ancestry, or whether these differences might be explained by correlated environmental factors, such as air pollution or life-style choices such as smoking." (PMID 38906890, 2024). "SAA1, FGA, SAP, and CETP can be potentially useful biomarkers for early diagnosis of EGPA and differential diagnosis of asthma." (PMID 37215720, 2023). "We have identified and validated four new potential serum biomarkers, including SAA1, FGA, SAP, and CETP, that can be used to distinguish EGPA from severe asthma." (PMID 35757752, 2022). "However, all the EGPA subjects we included were ANCA negative, and the result of decreased CETP levels in the EGPA group compared with the severe-asthma group suggests that the application of CETP may be useful for discriminating ANCA positive or negative EGPA." (PMID 35757752, 2022).
dyslipidaemia (6 papers, 2013 to 2025). "Numerous previous studies linked the CETP polymorphism to an increased risk of atherogenic dyslipidaemia, and thus, CVD." (PMID 37102051, 2023). "The ‘B1’ allele is believed to be associated with higher CETP activity, resulting in lower HDL and higher serum TG, and is considered a risk factor for dyslipidaemia." (PMID 35098451, 2022). "E3L.CETP mice on a chow diet represent an unique tool to study mechanisms of insidious progression of early adaptive to late maladaptive endothelial responses to humanised dyslipidaemia, with a distinct sex-dependent evolution of changes." (PMID 40240752, 2025). "It has been proposed that high CETP activity explains some of the high TG levels and low HDL-C levels (dyslipidaemia), observed in persons with MetS." (PMID 24206898, 2013).
endotoxemia (6 papers, 2016 to 2023). "Importantly, however, we could show that CETP expression was associated with a change in inflammatory burst and with earlier or higher mortality, both in polymicrobial infection and in acute endotoxemia models." (PMID 33500240, 2021). "Accordingly, in the present study, FPLC analysis showed that the reduction in HDL size and lipid content in the presence of CETP tended to be further pronounced during endotoxemia." (PMID 33500240, 2021). "During endotoxemia, HDL particle remodeling is associated with increased endothelial lipases and sPLA2 and decreased plasma cholesteryl ester transfer protein (CETP) and lecithin-cholesterol acyltransferase activity." (PMID 34087197, 2021). "Moreover, in mouse models, anacetrapib, a CETP inhibitor, reduced the severity of endotoxemia and improved survival by preserving the HDL-C and ApoA-I." (PMID 37621565, 2023). "Finally, the consequences of CETP expression on mouse survival after polymicrobial infection and endotoxemia were determined." (PMID 33500240, 2021).
hypothyroidism (6 papers, 2015 to 2025). Abnormally low levels of thyroid hormone. "Namely, studies involving human subjects and animal models have demonstrated that hypothyroidism is associated with decreased activities of cholesteryl-ester transfer protein (CETP), lecithin:cholesterol acyltransferase (LCAT), and HL." (PMID 31920978, 2019). "On the other hand, serum concentrations of cholesteryl ester transfer protein (CETP) transporter have been shown to be decreased significantly in patients with hypothyroidism." (PMID 34784265, 2022). "Hypothyroidism is associated with decreased CETP and hepatic lipase activity, which does not allow hydrolysis of HDL, leading to an increase in HDL levels." (PMID 40937266, 2025). "Since CETP plays an important role in suppressing serum levels of HDL-C, the positive modulatory role of thyroid hormones in CETP could make a reasonable explanation which elucidates the alterations of serum HDL-C in patients with hypothyroidism." (PMID 34784265, 2022). "In addition, suppressed biological activity of CETP and phospholipid transfer protein has been shown to induce the decreased serum contents of HDL-2 but the increased serum contents of HDL-3 in patients with hypothyroidism." (PMID 34784265, 2022). "Moreover, increased HDL level may be contributed to the cholesteryl ester transfer protein (CETP) decreased activity, which transfers cholesterol from HDL-C to LDL-C, and to a very low-density lipoprotein (VLDL) as observed in hypothyroidism." (PMID 30927245, 2020).
ischemic stroke (6 papers, 2017 to 2024). A stroke disorder caused by obstruction of blood flow to the brain, due to thrombotic (local blood clot formation) or embolic (due to a blood clot or other material traveling from another site) event. "Four hundred eight patients with ischemic stroke and 347 unrelated healthy individuals of age and sex matched were genotyped for Apolipoprotein A5 (ApoA5), lipoprotein lipase (LPL), Cholesteryl ester transfer protein (CETP) and low-density lipoprotein receptor (LDL-R) genes." (PMID 28623937, 2017).